RNU4ATAC (RNA, U4atac small nuclear)
Synonyms: RNU4ATAC1; U4atac; LWS; MOPD1; RFMN; TALS
Gene: Small nuclear RNA gene on chromosome 2 (121,530,880 to 121,531,009, forward strand). Ensembl gene ENSG00000264229.
Pathways (Reactome):
Gene expression (Transcription): RNA polymerase II transcribes snRNA genes
Gene Ontology:
Molecular function: pre-mRNA 5'-splice site binding; U6atac snRNA binding
Biological process: mRNA 5'-splice site recognition; spliceosomal tri-snRNP complex assembly
Cellular component: U4atac snRNP
Gene-disease validity (ClinGen):
ClinGen rates the evidence that RNU4ATAC causes each of these diseases.
RNU4ATAC spectrum disorder (autosomal recessive): Definitive. A syndromic disease characterized by growth restriction, microcephaly, skeletal dysplasia, and cognitive impairment.
Diseases named in the same sentence as RNU4ATAC in open-access papers:
RNU4ATAC is named in the same sentence as 14 diseases in open-access papers, as found by Europe PMC text mining. Sharing a sentence is not in itself a finding about the gene and the disease. The quoted sentences say what the papers report.
microcephalic osteodysplastic primordial dwarfism type I (6 papers, 2013 to 2021). A microcephalic osteodysplastic primordial dwarfism that has material basis in homozygous or compound heterozygous mutation in the RNU4ATAC gene, encoding a small nuclear RNA (snRNA) component of the U12-dependent (minor) spliceosome, on chromosome 2q14.2. "RNU4ATAC rare variants have been recently reported to cause microcephalic osteodysplastic primordial dwarfism, type I (MOPD1), whose phenotype is distinct from Roifman Syndrome." (PMID 26522830, 2015). "Importantly, mutations in RNU4ATAC have been shown to affect the formation of minor spliceosome and cause Taybi-Linder syndrome/microcephalic osteodysplastic primordial dwarfism type 1 (TALS/MOPD1), illustrating that not only malfunctioning of proteins but also of U snRNAs can cause disease." (PMID 31671093, 2019).
Roifman syndrome (5 papers, 2015 to 2022). "It should be noted that Roifman syndrome-causative compound heterozygous RNU4ATAC variants comprise one variant that is located within MOPD1-implicated structural elements and one variant that is located outside of MOPD1-implicated structural elements." (PMID 29370840, 2018). "In addition, Roifman Syndrome causal variants always present a characteristic compound heterozygosity pattern: one variant affects RNU4ATAC elements already implicated in MOPD1, while the other variant affects a newly disease-implicated yet highly conserved element, the stem II." (PMID 26522830, 2015). "The RNU4ATAC structural elements perturbed in MOPD1 and Roifman Syndrome suggest a molecular basis for the phenotypic differences between the two syndromes." (PMID 26522830, 2015). "However, some MOPD1/TALS and Roifman syndrome patients (caused by mutations in RNU4ATAC) present with cardiac defects, including coarctation of aorta, Tetralogy of Fallot, atrial septal defect, ventricular septal defect and non-compaction of the heart." (PMID 34859816, 2022).
RNU4ATAC also shares sentences with these, for which no sentence is quoted: microcephaly (6 papers); antibody deficiency (1); atrial septal defect (1); autosomal recessive disease (1); brain malformations (1); cognitive delay (1); dwarfism (1); Epiphyseal dysplasia (1); Retinal dysplasia (1); Retinal dystrophy (1); Tetralogy of Fallot (1); ventricular septal defect (1).